ENSG00000286192 (Novel protein)
Gene: Protein-coding gene on chromosome 7 (1,815,804 to 2,242,215, reverse strand). Ensembl gene ENSG00000286192.
Genetic constraint (gnomAD): Missense variants: 128 observed, 139.75 expected, observed/expected ratio (o/e) 0.92, 90% interval 0.79 to 1.06. Synonymous variants: 56 observed, 56.68 expected, observed/expected ratio (o/e) 0.99, 90% interval 0.8 to 1.23.